PRDM12 (PR/SET domain 12)
Description:
Transcriptional regulator necessary for the development of nociceptive neurons, playing a key role in determining the nociceptive lineage from neural crest cell progenitors. Initiates neurogenesis and activates downstream pro-neuronal transcription factors, such as NEUROD1, BRN3A, and ISL1, specifically within nociceptive neurons, while repressing non-nociceptor cell fates. Essential for the proper function of nociceptors in adults, influencing both their excitability and their gene expression, thereby impacting how these neurons respond to various pain stimuli.
Synonyms: PFM9; HSAN8
Tractability: No criterion of Open Targets' tractability assessment is met for any kind of drug.
Target class: Enzyme; Transferase
Gene: Protein-coding gene on chromosome 9 (130,664,594 to 130,682,986, forward strand). Ensembl gene ENSG00000130711.
Subcellular location: Nucleus
Subcellular location (Human Protein Atlas): Nucleoplasm
Gene Ontology:
Molecular function: histone chaperone activity; histone methyltransferase binding; DNA-binding transcription activator activity, RNA polymerase II-specific; DNA-binding transcription repressor activity, RNA polymerase II-specific; DNA-binding transcription factor activity, RNA polymerase II-specific
Biological process: detection of temperature stimulus involved in sensory perception of pain; neuron projection development; protein methylation; sensory perception of pain; negative regulation of transcription by RNA polymerase II; neurogenesis; neuron fate specification; regulation of gene expression; neuron differentiation; positive regulation of transcription by RNA polymerase II
Cellular component: nucleus
Genetic constraint (gnomAD): Loss-of-function variants: 17 observed, 22.11 expected, observed/expected ratio (o/e) 0.77, 90% interval 0.52 to 1.15. The upper end of that interval is the gene's LOEUF score, 1.15, which puts it in group 5 of 6, group 1 being the genes least tolerant of losing a copy. Missense variants: 384 observed, 397.51 expected, observed/expected ratio (o/e) 0.97, 90% interval 0.89 to 1.05. Synonymous variants: 211 observed, 179.23 expected, observed/expected ratio (o/e) 1.18, 90% interval 1.05 to 1.32.
Homologues: Orthologues: chimpanzee PRDM12 (99% identical), macaque PRDM12 (99% identical), dog PRDM12 (98% identical), pig PRDM12 (98% identical), mouse Prdm12 (98% identical), rat Prdm12 (98% identical), rabbit PRDM12 (88% identical), tropical clawed frog prdm12 (85% identical), guinea pig PRDM12 (84% identical), zebrafish prdm12b (81% identical). Paralogues in human: ZNF683 (23% identical), ZBTB49 (22% identical), ZBTB7B (17% identical), BCL6 (16% identical), FEZF1 (16% identical), BCL6B (15% identical), FEZF2 (15% identical), PRDM13 (14% identical), GFI1B (13% identical), GFI1 (13% identical), ZNF280D (13% identical), ZBTB21 (12% identical), and 16 more.
Diseases named in the same sentence as PRDM12 in open-access papers:
PRDM12 is named in the same sentence as 28 diseases in open-access papers, as found by Europe PMC text mining. Sharing a sentence is not in itself a finding about the gene and the disease. The quoted sentences say what the papers report.
congenital pain insensitivity (3 papers, 2020 to 2025). "Mutation in human PRDM12 has been found in patients with congenital pain insensitivity (CIP)." (PMID 33291744, 2020).
chronic myeloid leukemia (2 papers, 2010 to 2021). "GPR123 and KNDC1 have recently been shown to be mutated in acute myeloid leukemia by using whole-genome sequencing methodology, whilst PRDM12 is located in a minimal commonly deleted region in chronic myeloid leukemia." (PMID 20184741, 2010). "Although little is known about the function of PRDM12 in oncogenesis, previous studies showed that PRDM12 might act as a tumor suppressor gene in human chronic myeloid leukemia (CML)." (PMID 34769459, 2021).
colon cancers (1 paper, 2023). "However, several studies indicated that PRDM12 is upregulated in prostate and colon cancers compared to normal tissues." (PMID 36982660, 2023).
corneal opacities (1 paper, 2022). "We found that patients with PRDM12 variant had more severe manifestations of ocular surface disease, with more prevalent corneal opacities and worse visual acuity, compared to patients with SCN9A variant." (PMID 36111846, 2022). "Similar results regarding corneal blink reflex and corneal opacities were reported in other patients with PRDM12 variants." (PMID 36111846, 2022).
Frey syndrome (1 paper, 2024). An autonomic disorder characterized by excessive sweating of the forehead, upper lip, perioral region, or sternum subsequent to gustatory stimuli. "In the previously reported family with congenital bilateral Frey syndrome, one (asymptomatic) parent and both affected girls had a heterozygous seven-base pair deletion in the terminal exon of PRDM12 (c.717delCGCGGGC p.Pro239Profs228*)." (PMID 38591490, 2024).
Hereditary sensory autonomic neuropathy type VIII (1 paper, 2024). "Hereditary sensory autonomic neuropathy type VIII (HSAN-VIII) is a rare genetic disease that occurs due to mutations in the PRDM12 gene." (PMID 38685849, 2024).
keratitis (1 paper, 2023). A corneal disease that is characterized by inflammation of the cornea. "Patients with PRDM12 mutations present with reduced tear secretion, corneal abrasions, and loss of corneal reflexes, resulting in keratitis and corneal scarring." (PMID 37021010, 2023).
Obesity (1 paper, 2021). Accumulation of substantial excess body fat. "The study population could be useful to define whether PRDM12 polymorphisms represent a risk factor for obesity under permissive environmental conditions." (PMID 34769459, 2021). "Moreover, the disclosure of the PRDM12 mechanism of action in food intake and energy balance could have a relevant impact for the identification of new strategies to counteract obesity." (PMID 34769459, 2021). "Adult mice of both sexes selectively lacking Prdm12 from POMC neurons, showed a considerable reduction in Pomc mRNA levels that led to an amplified food intake, adiposity and bodyweight gain, as well as early-onset obesity that recapitulated symptoms of human POMC deficiency." (PMID 34769459, 2021).
prostate adenocarcinoma (1 paper, 2014). "The PRDM sub-group of PMTs is overwhelmingly repressed across multiple cancer types, suggesting tumor suppressor activity, but PRDM12 is among the most overexpressed genes in prostate adenocarcinoma (log2 tumor versus matched control >1 in 66% patients)." (PMID 25484917, 2014).
prostate carcinoma (1 paper, 2021). A carcinoma that arises from epithelial cells of the prostate gland. "Additionally, the integrated analysis of abnormalities of HMTs encoding genes in prostate cancer from TCGA, identified a role for PRDM12 in the pathogenesis of this cancer type." (PMID 34769459, 2021). "Our pan-cancer meta-analysis based on The Cancer Genome Atlas (TCGA) data showed that PRDM12 was upregulated in several cancer types: colon, breast, kidney, colon, lung, liver, thyroid, ovary and prostate cancers, suggesting that it could represent a putative tumor marker." (PMID 34769459, 2021).
tumor (7 papers, 2010 to 2025). "Although preliminary lines of evidence suggest that PRDM12 is endowed with a tumor-promoting function, several aspects should be investigated to define the role of PRDM12 in cancer." (PMID 34769459, 2021). "Cancer tissue specimen analysis by immunohistochemistry could be useful to establish if a correlation among PRDM12 expression, with grading, tumor size, biomarkers serum levels, tumor vascular invasion, overall survival and prognosis, exists." (PMID 34769459, 2021). "Therefore, further studies investigating the involvement of PRDM12 in malignancies and its possible use as a tumor biomarker are warranted." (PMID 32290321, 2020). "Several studies indicated that PRDM12 might act as a tumor suppressor gene in human chronic myeloid leukemia with derivative chromosome 9 deletions or rearrangements." (PMID 32290321, 2020). "Previous studies suggested that PRDM12 may act as a tumor suppressor in patients with CML." (PMID 36982660, 2023). "Of note, TCGA gene expression profiling of PRDM genes revealed significant overexpression of PRDM12 and PRDM13 in many tumor types whereas ZFPM2/FOG2, PRDM8, and PRDM16 were more often downregulated in tumor tissues." (PMID 30347759, 2018).
cancer (6 papers, 2014 to 2024). A tumor composed of atypical neoplastic, often pleomorphic cells that invade other tissues. "The mutational profiling analyses of PRDM12 gene across human cancers revealed 72 mutations, 30 of which were detrimental somatic mutations (frameshift, in-frame deletions, stop gained and start lost mutations; splice site, UTR, and intron variants)." (PMID 34769459, 2021). "The H-score levels of the protein expression levels of MECOM and PRDM11 were significantly higher in UCEC tissue, whereas the H-scores of PRDM1 and PRDM12 were weakened or undetectable in cancer tissue." (PMID 39468462, 2024). "PRDM12 gene amplification induced an mRNA expression level increase in cancer cells compared to adjacent normal ones." (PMID 34769459, 2021). "Our previous pan-cancer analysis on TCGA data showed that PRDM12 is upregulated in many tumors including colon cancer and interestingly, is not expressed in adult normal tissues." (PMID 32290321, 2020). "Moreover, we attempt to provide insights for the future study of the signaling pathway(s) involving PRDM12 and to clarify its role in cancer onset and progression." (PMID 34769459, 2021). "Moreover, we wish to highlight the importance of future studies focusing on the PRDM12 signaling pathway(s) and its role in cancer onset and progression." (PMID 34769459, 2021). "Moreover, integrated analysis of genetic abnormalities of the KMT in PC from TCGA, identified PRDM12 as a gene with a pathogenetic role in this type of cancer." (PMID 32290321, 2020). "Our pan-cancer study has also identified PRDM12 as a possible epi-driver gene in multiple cancers." (PMID 30347759, 2018). "Of note, these cancer specimens showed measurable levels of PRDM12." (PMID 30347759, 2018). "Targeting PRDM12 and its transcriptional program could have a high therapeutic potential, representing a promising strategy to overcome resistance and selectively target cancer cells." (PMID 34769459, 2021). "Specifically, PRDM12 and PRDM13 were largely overexpressed in many cancers whereas PRDM16 and ZFPM2/FOG2 were often downregulated." (PMID 30347759, 2018). "Accordingly, PRDM12 is not expressed in adult normal tissues, even though its expression is re-activated in several cancer types." (PMID 34769459, 2021). "PRDM12 is not usually expressed in adult normal tissues but its expression is re-activated in several cancer types." (PMID 34769459, 2021). "Currently, little information is available on PRDM12 expression in cancers and its mechanism of action have not been described thus far." (PMID 34769459, 2021). "PRDM12 is a member of the PRDI-BF1 (positive regulatory domain I-binding factor 1) homologous domain (PRDM)-containing protein family, a subfamily of Kruppel-like zinc finger proteins, controlling key processes in the development of cancer." (PMID 34769459, 2021). "However, the promoter methylation levels of PRDM3, PRDM4, PRDM6, PRDM11, and PRDM12 do not show significant differences across all cancer types." (PMID 39468462, 2024). "However, little information is currently available on PRDM12 expression in cancers and its mechanism of action has not been thoroughly described." (PMID 34769459, 2021). "Noteworthy is that when we measured the differential expression of PRDM12 in cDNA panel arrays, we found the expression of this gene only in cancer specimens but not in healthy samples of several tissues, suggesting that it could be putatively utilized as a biomarker in those malignancies." (PMID 30347759, 2018).
peripheral neuropathies (1 paper, 2021). "PGP9.5 immunostaining is considered as a diagnostic tool in the study of peripheral neuropathies, which, in PRDM12-CIP case, revealed the absence of PGP9.5 reactive nerve endings in patient epidermis." (PMID 34646120, 2021).
PRDM12 also shares sentences with these, for which no sentence is quoted: neuropathy (2 papers); acute myeloid leukemia (1); Anosmia (1); Anxiety (1); colon adenocarcinoma (1); corneal ulcer (1); erythropoietic protoporphyria (1); genetic disease (1); Hyperhidrosis (1); Lesch-Nyhan syndrome (1); lung carcinoma (1); lung fibrosis (1); lymph node metastasis (1); staphylococcus aureus infection (1); uterine corpus endometrial carcinoma (1).